EEF1AKMT4-ECE2 (EEF1AKMT4-ECE2 readthrough)
Description:
Converts big endothelin-1 to endothelin-1. May also have methyltransferase activity (By similarity). May play a role in amyloid-beta processing (By similarity).
Tractability: Antibody: UniProt predicts a signal peptide or a membrane-spanning region; its Gene Ontology location is reachable by antibodies, with medium confidence. PROTAC: ubiquitination databases record sites on it.
Gene: Protein-coding gene on chromosome 3 (184,249,695 to 184,293,031, forward strand). Ensembl gene ENSG00000284917.
Subcellular location: Golgi apparatus membrane; Cytoplasmic vesicle, secretory vesicle membrane
Subcellular location (Human Protein Atlas): Cytosol; Nucleoplasm
Gene Ontology:
Molecular function: metalloendopeptidase activity; metallopeptidase activity
Biological process: brain development; cardioblast differentiation; heart development; protein processing; peptide hormone processing; proteolysis
Cellular component: Golgi membrane; plasma membrane; transport vesicle membrane
Genetic constraint (gnomAD): Loss-of-function variants: 84 observed, 113.81 expected, observed/expected ratio (o/e) 0.74, 90% interval 0.62 to 0.88. The upper end of that interval is the gene's LOEUF score, 0.88, which puts it in group 3 of 6, group 1 being the genes least tolerant of losing a copy. Missense variants: 1,042 observed, 1,187.7 expected, observed/expected ratio (o/e) 0.88, 90% interval 0.83 to 0.92. Synonymous variants: 464 observed, 486.49 expected, observed/expected ratio (o/e) 0.95, 90% interval 0.88 to 1.03.